TFRC (transferrin receptor)
Diseases named in the same sentence as TFRC in open-access papers (continued):
Sharing a sentence is not in itself a finding about the gene and the disease.
Renal cyst (1 paper, 2024). A fluid filled sac in the kidney. "In patients with renal cysts, the serum levels of ferritin, transferrin receptor-1, creatinine, and uric acid at the time of diagnosis were comparable to the values detected at baseline (p > 0.05)." (PMID 39335726, 2024).
sarcopenia (1 paper, 2025). Progressive decline in muscle mass due to aging which results in decreased functional capacity of muscles. "In a mouse model of sarcopenia, researchers found that TFRC ablation in muscle satellite cells impairs muscle regeneration while promoting both labile iron accumulation and lipogenesis." (PMID 40427725, 2025).
seminoma (1 paper, 2025). A radiosensitive malignant germ cell tumor found in the testis (especially undescended), and extragonadal sites (anterior mediastinum and pineal gland). "This study investigates the immunolabeling of key iron-related proteins (Transferrin Receptor 1, Transferrin Receptor 2, and Ferritin Heavy chain 1) and Proliferating Cell Nuclear Antigen (PCNA) in canine SCO tubules within distinct microenvironments: seminomas, Sertoli cell tumors, and isolated." (PMID 40427255, 2025).
skin cancer (1 paper, 2023). "Possible overexpressed receptors that may be candidates for active targeting in skin cancers are folate receptor α isoform, transferrin receptor 1 (TfR1), CD44 surface markers for hyaluronic acid, and other proteins." (PMID 37232944, 2023).
soft tissue sarcoma (1 paper, 2023). A malignant neoplasm arising from muscle tissue, adipose tissue, blood vessels, fibrous tissue, or other supportive tissues excluding the bones. "In addition, analysis of a CCLE dataset revealed upregulation of the TFRC protein level in soft tissue sarcoma cell lines." (PMID 37444594, 2023).
squamous non-small-cell lung cancer (1 paper, 2023). "The predictive role of transferrin receptor protein as a biomarker for immune checkpoint inhibitors in non-squamous non-small-cell lung cancer with low programmed death-ligand 1 expression was validated in an independent cohort." (PMID 37760429, 2023).
Streptococcus pneumonia (1 paper, 2022). "In Kenyan infants, higher TSAT predicted a stronger antibody response after vaccination against Corynebacterium diphtheriae and Streptococcus pneumonia while a lower transferrin receptor level was associated with a stronger antibody response after vaccination against poliovirus." (PMID 36618359, 2022).
synovial sarcoma (1 paper, 2023). "Immunostaining of eight paraffin-embedded synovial sarcoma specimens revealed that seven specimens were positive for TFRC, and all eight specimens were positive for FTH1, suggesting abundant iron uptake and storage in synovial sarcoma cells." (PMID 37444594, 2023). "Furthermore, seven of eight synovial sarcoma clinical samples were positive for TFRC expression, and all eight were positive for FTH1 expression." (PMID 37444594, 2023). "Furthermore, an analysis of patients with synovial sarcoma treated in our institute revealed a significant correlation between high TFRC mRNA expression and poor OS for both the full cohort (n = 39, p < 0.005) and the cohort of patients with advanced-stage disease (n = 13, p < 0.05)." (PMID 37444594, 2023). "Moreover, transferrin receptor 1 (TFRC) and SHANK-associated RH domain interactor (SHARPIN), both of which are oncogenic factors and related to poor overall survival, are highly expressed, particularly in synovial sarcoma cell lines." (PMID 37444594, 2023).
trypanosomiasis (1 paper, 2013). Infection with protozoa of the genus trypanosoma. "This structural difference to the human transferrin receptor makes this pathway a good target to develop chemotherapy against human trypanosomiasis." (PMID 25937964, 2013).
viral hemorrhagic fever (1 paper, 2020). A viral infectious disease caused by RNA viruses in the Arenaviridae, Bunyaviridae, Filoviridae, or Flaviviridae family, and characterized by a severe multisystem syndrome, with damage to the vascular system and hemorrhaging. "A feature of all NWMs that cause viral hemorrhagic fever is the use of human transferrin receptor 1 (hTfR1) for cellular entry." (PMID 32452770, 2020).
tumor (680 papers, 1985 to 2026). "TFRC encodes the transferrin receptor (TfR), a protein critical for mediating cellular iron uptake and regulating ferroptosis in various tumor cells." (PMID 41278282, 2025). "This suggests that the high expression of TFRC reduces immune cell recruitment, which is closely associated with tumor immunosuppression." (PMID 40303995, 2025). "TFRC depletion significantly diminished the cytotoxic effects of artesunate in vivo, as evidenced by reduced tumor growth in TFRC-deficient xenografts." (PMID 40946428, 2025). "For example, the transcription factor hypoxia-inducible factor (HIF) has been implicated in the upregulation of TFRC in response to low oxygen levels, a common feature in the tumor microenvironment." (PMID 40303995, 2025). "Consistently, L. reuteri restored GPX4 expression and reduced the ferroptosis-associated upregulation of TFRC expression in tumor tissues, thereby recapitulating the biochemical fingerprint of I3A treatment." (PMID 41354345, 2025). "When ferroportin (FPN/SLC40A1) levels are low and transferrin receptor 1 (TfR1) levels are high, iron accumulates in tumour-associated macrophages (TAMs) and colon epithelial cells (TECs), preventing iron from being exported normally." (PMID 41153383, 2025). "By estimating the relative abundance of immune cell populations using the ssGSEA algorithm based on the TCGA database, we found that low TFRC expression was positively associated with increased infiltration of cytotoxic CD8+ T cells into tumour tissues." (PMID 39095323, 2024). "Higher expression of TFRC is associated with a better response to selumetinib and cobimetinib, and poorer sensitivity of tumor cells to everolimus, dasatinib, erlotinib, and lenvatinib." (PMID 37940859, 2023). "For instance, transferrin receptor 1 (TFR1), which is a carrier in the regulation of cell growth as well as iron uptake, is aberrantly expressed in tumors and is intimately linked to tumour proliferation as well as metastasis." (PMID 37957566, 2023). "Abnormal regulation of iron‐related proteins, such as transferrin (TRF), transferrin receptor 1 (TfR1) and ferritin, can cause iron overload and sensitise tumour cells to ferroptosis." (PMID 35220675, 2022). "Transferrin receptor is often overexpressed in cancer cells (e.g., brain, liver, breast, lung, and colon) since iron is associated with the proliferation and survival of tumor cells." (PMID 35456655, 2022). "The expression of transferrin receptor (TfR) is higher in tumor cells as compared with normal cells and is associated with the increased iron demand in rapidly proliferating cancer cells, as well as, folate receptors were expressed." (PMID 35946342, 2022). "In this study, our research showed that the high expression of TFRC has been associated with tumor-infiltrating lymphocyte (TIL) levels (CD8 + T cell, Macrophage cell) and immune checkpoints, suggesting a novel immunotherapy target." (PMID 36483569, 2022). "Transferrin receptors (TfR) are overexpressed on many malignant tumor cells, whereas normal cells are deficient in this type of receptor." (PMID 33321722, 2020). "TFRC, whose expression has been associated with poor prognosis and tumor progression, was found over-expressed in females." (PMID 32849808, 2020). "Effectively, in HCC tumors, the increased expression levels of Fe-related FLVCR1 and TFRC genes were associated with various factors leading to poor prognosis such as vascular invasion and the histological grade of the tumor for FLVCR1." (PMID 33255972, 2020). "Repression of nitrogen fixation 1 (NFS1) predisposes tumor cells to ferroptosis by activating the iron-starvation response via stabilizing TFRC transcription and inhibiting ferritin heavy chain 1 (FTH1) translation." (PMID 33425217, 2020). "The revealed genes EFNA1 and TFRC encode ephrin A1 and the transferrin receptor, which play an important role in tumor development through inducing tumor angiogenesis and iron uptake, respectively." (PMID 31523389, 2019).
tumor (continued). "The two remaining genes encode for EGFR and TFRC, two sialoglycoproteins equally expressed in the tumor group and the astrocyte group." (PMID 25360666, 2014). "More recently, increased TFR1 expression has been linked to tumor microenvironment (TME) infiltration by immune effectors in selected tumors, but a comprehensive assessment of the genomic landscape associated TFRC (the gene encoding TFR1) expression has not been conducted." (PMID 42122198, 2026). "TFRC has emerged as a significant target in cancer therapy due to its overexpression in various malignancies, which is often associated with increased cellular iron uptake necessary for rapid tumor growth." (PMID 40303995, 2025). "To address the efficacy of thiostrepton, we showed that thiostrepton could induce ROS and activate the expression of the transferrin receptor in the tumor‐associated bacteria colonized tumors." (PMID 39135304, 2024). "Furthermore, lower expression levels of SCD, SQLE, FADS2 and TFRC were significantly associated with increased tumor infiltration of DCs and/or B cells." (PMID 35818395, 2022). "Therefore, we illustrated the association between TFRC expression and the tumor prognosis, clinical–pathological parameters, immunity, tumor mutational burden (TMB), and m6A modification in RNA." (PMID 36483569, 2022). "Therefore, the increased expression of transferrin receptor causes an increase in iron ion uptake, then enhancing the effect of artemisinin on tumor cells." (PMID 32452511, 2020). "Moreover, genetic and pharmacological inhibition of iron-related genes (e.g., HO-1, TfR1, and FTH1, which encode heme oxygenase-1, transferrin receptor 1, and ferritin, respectively) can inhibit ferroptosis in tumor cells." (PMID 28657578, 2017). "In this context, bsAbs are engineered to bind both a surface protein involved in tumor growth or survival and a secondary molecule that facilitates internalization and subsequent degradation of the target, such as membrane-associated E3 ubiquitin ligases or the transferrin receptor." (PMID 41211166, 2025). "Tumor cells highly express the transferrin receptor (TfR1), which absorbs more iron to meet their rapid proliferation requirements." (PMID 41355972, 2026). "Transferrin receptor (TfR) targeting is effective in GBM due to its overexpression in tumor cells and the BBB." (PMID 41574218, 2026). "Tumor cells exploit the transferrin-transferrin receptor (TFRC) axis to competitively limit macrophage iron uptake, lowering intracellular ferrous iron." (PMID 41355954, 2026). "CD71 takes part in this circuitry because HIF-1 and NF-κB crosstalk can drive TFRC transcription under hypoxia/inflammation, wiring iron import directly into the core network that sustains tumor growth and adaptation." (PMID 41375568, 2025). "The relationship between TFRC and immune cell function is a critical aspect of the tumor microenvironment (TME) that influences cancer progression and treatment outcomes." (PMID 40303995, 2025). "By limiting iron availability, LF also affects tumor metabolism—it reduces ferritin and transferrin receptor 1 (TfR1) expression, which limits iron uptake by cancer cells, while increasing ferroportin levels, facilitating the removal of iron from cells." (PMID 40286136, 2025). "The restructured nanodevice enabled oligomerization of c-Met and transferrin receptor, which inhibited tumor metastasis by blocking the hepatic growth factor (HGF)/c-Met signaling pathway." (PMID 40041032, 2025). "We have demonstrated that PTPN2 promotes mitochondrial renewal through PINK1‐PRKN‐dependent mitophagy by suppressing TFRC expression, thereby exerting tumor‐promoting effects in ALK+ ALCL." (PMID 40734623, 2025). "SERPINB5, SFRP1, and TFRC showed elevated expression levels in PAAD tumor samples compared to normal samples." (PMID 41595468, 2025). "Further experiments demonstrated that AC484 exerted anti‐tumor activities by TFRC‐mediated PINK1‐PRKN‐dependent mitophagy." (PMID 40734623, 2025).
tumor (continued). "The transferrin receptor probe localized primarily to the liver when administered i.v., with the signal also detected in the tumor-burdened ovary." (PMID 41322193, 2025). "To clarify TFRC expression across various cancers, we analyzed 33 tumor types from the TCGA pan-cancer dataset." (PMID 40303995, 2025). "Conversely, following i.p. administration, the highest signal for the IVISense Transferrin Receptor 750 probe was in tumor-burdened tissue (fat pads, omentum, and mesentery), making i.p. delivery superior for the transferrin receptor probe." (PMID 41322193, 2025). "Subsequent IHC analysis of GPX4, FTH1 and TFRC expression in subcutaneous tumours from DLBCL xenograft model yielded similarly results." (PMID 40038872, 2025). "Emerging treatment strategies, including iron chelation therapy, ferroptosis induction, and transferrin receptor-targeted therapies, have demonstrated promising anti-tumor effects in preclinical models." (PMID 40486542, 2025). "Fluorescent transferrin receptor probe and folate receptor probe localization 24 h post-imaging agent injection in the two mice supported high probe accumulation in tumor-bearing tissues (fat pads, omentum, ovary, and mesentery) of the untreated mouse." (PMID 41322193, 2025). "It facilitates lipid peroxidation and oxidative stress by degrading ferritin and inducing the expression of transferrin receptor 1 (TfR1), which subsequently promotes ferroptosis in tumor cells." (PMID 40066330, 2025). "HFn can selectively deliver a large amount of cargo into tumors in vivo via transferrin receptor 1 (TfR1)-mediated tumor-cell-specific targeting followed by rapid internalization." (PMID 41368585, 2025). "Ferritin nanocages (FNs) have been widely used in tumor drug delivery due to their ability to target transferrin receptor 1 (TfR1)." (PMID 40395752, 2025). "Previous research has shown that transferrin receptor 1 (TFR1) and STAT3 signaling are closely linked to iron metabolism and tumor immune escape." (PMID 41551164, 2025). "Collectively, these results demonstrated that AC484 exerted anti‐tumor effects by modulating TFRC expression, which in turn disrupted PINK1‐PRKN‐dependent mitophagy." (PMID 40734623, 2025). "These systems can be engineered to enhance cellular uptake through receptor-mediated endocytosis, leveraging the overexpression of TFRC in tumor cells." (PMID 40303995, 2025). "used peptide T7, which targets the transferrin receptor (TfR) that is overexpressed in brain capillary endothelial cells and many malignant tumor cells, and is significantly more present than in normal cells." (PMID 39866911, 2025). "Increased IRP2 levels stabilise TFRC mRNA, leading to sustained expression of transferrin receptors and, consequently, enhanced iron uptake by tumour cells." (PMID 41153383, 2025). "In vivo experiments reinforced our in vitro findings, with artesunate showing substantial anti-tumor activity in a TFRC-dependent manner." (PMID 40946428, 2025). "At the tumor level, high iron demand due to rapid proliferation, upregulation of transferrin receptor 1, and downregulation of ferroportin promote iron sequestration within tumor cells, reducing circulating iron." (PMID 41190142, 2025). "Human ferritin H-type (HFt) is a promising NP for drug delivery, particularly chemotherapeutics, due to its internalisation by the transferrin receptor 1 (CD71), frequently overexpressed in tumours." (PMID 41198629, 2025). "First, ferritin expression and transferrin-receptor expression were explored to investigate their regulation after enhanced tumor apoptosis." (PMID 40436830, 2025). "SERPINB5, SFRP1, and TFRC exhibited higher expression levels in PAAD tumor samples, consistent with the gene expression data from the HPA database." (PMID 41595468, 2025). "On day 26 post-tumor challenge, folate-receptor- and transferrin-receptor-targeted imaging agents were administered to the mice and evaluated as indicators of tumor burden." (PMID 41322193, 2025).